NNMT (nicotinamide N-methyltransferase)
Description:
Catalyzes the N-methylation of nicotinamide using the universal methyl donor S-adenosyl-L-methionine to form N1-methylnicotinamide and S-adenosyl-L-homocysteine, a predominant nicotinamide/vitamin B3 clearance pathway. Plays a central role in regulating cellular methylation potential, by consuming S-adenosyl-L-methionine and limiting its availability for other methyltransferases. Actively mediates genome-wide epigenetic and transcriptional changes through hypomethylation of repressive chromatin marks, such as H3K27me3. In a developmental context, contributes to low levels of the repressive histone marks that characterize pluripotent embryonic stem cell pre-implantation state. Acts as a metabolic regulator primarily on white adipose tissue energy expenditure as well as hepatic gluconeogenesis and cholesterol biosynthesis. In white adipocytes, regulates polyamine flux by consuming S-adenosyl-L-methionine which provides for propylamine group in polyamine biosynthesis, whereas by consuming nicotinamide controls NAD(+) levels through the salvage pathway (By similarity). Via its product N1-methylnicotinamide regulates protein acetylation in hepatocytes, by repressing the ubiquitination and increasing the stability of SIRT1 deacetylase (By similarity). Can also N-methylate other pyridines structurally related to nicotinamide and play a role in xenobiotic detoxification.
Tractability: Small molecule: a structure with a bound ligand is known; a high-quality ligand is known; it has a binding pocket of medium quality; it belongs to a druggable protein family. PROTAC: ubiquitination databases record sites on it; its protein half-life has been measured; a small molecule that binds it is known.
Target class: Enzyme; Transferase
Gene: Protein-coding gene on chromosome 11 (114,257,765 to 114,314,329, forward strand). Ensembl gene ENSG00000166741.
Subcellular location: Cytoplasm
Subcellular location (Human Protein Atlas): Golgi apparatus; Cytosol
Pathways (Reactome):
Metabolism: Metabolism of ingested SeMet, Sec, MeSec into H2Se; Methylation; Nicotinate metabolism
Gene Ontology:
Molecular function: nicotinamide N-methyltransferase activity; pyridine N-methyltransferase activity; methyltransferase activity; S-adenosylmethionine-dependent methyltransferase activity
Biological process: nicotinamide metabolic process; methylation; nicotinate metabolic process; positive regulation of gluconeogenesis; positive regulation of protein deacetylation; NAD+ catabolic process
Cellular component: cytosol; cytoplasm
Genetic constraint (gnomAD): Loss-of-function variants: 10 observed, 12.98 expected, observed/expected ratio (o/e) 0.77, 90% interval 0.47 to 1.31. The upper end of that interval is the gene's LOEUF score, 1.31, which puts it in group 5 of 6, group 1 being the genes least tolerant of losing a copy. Missense variants: 381 observed, 334.36 expected, observed/expected ratio (o/e) 1.14, 90% interval 1.05 to 1.24. Synonymous variants: 143 observed, 140.65 expected, observed/expected ratio (o/e) 1.02, 90% interval 0.89 to 1.17.
Homologues: Orthologues: chimpanzee NNMT (99% identical), macaque NNMT (97% identical), pig NNMT (88% identical), dog NNMT (86% identical), mouse Nnmt (85% identical), guinea pig NNMT (81% identical), rat Nnmt (81% identical), zebrafish zgc:64002 (39% identical), Caenorhabditis elegans anmt-2 (25% identical), Caenorhabditis elegans anmt-3 (25% identical), Caenorhabditis elegans anmt-1 (23% identical). Paralogues in human: INMT (53% identical), PNMT (36% identical).
Diseases named in the same sentence as NNMT in open-access papers:
NNMT is named in the same sentence as 138 diseases in open-access papers, as found by Europe PMC text mining. Sharing a sentence is not in itself a finding about the gene and the disease. The quoted sentences say what the papers report.
Obesity (56 papers, 2015 to 2025). Accumulation of substantial excess body fat. "Single nucleotide variants (SNVs) in the NNMT gene have been linked to metabolic disturbances and increased risk of obesity, type 2 diabetes mellitus, hyperlipidemia, and hypertension —all well-established CVD risk factors." (PMID 41008588, 2025). "Single nucleotide variants in the NNMT gene are significantly correlated with disturbances in energy metabolism, obesity, type 2 diabetes (T2D), hyperlipidemia, and hypertension." (PMID 38919254, 2024). "Our previous research investigated the association between NNMT gene sequence variants and obesity, revealing significant findings." (PMID 38919254, 2024). "The findings indicate that NNMTi is a promising inhibitor that targets NNMT and can reverse the obesity induced by diet and prevent the associated T2D." (PMID 38919254, 2024). "Reported a significantly correlation of the variant rs694539 of the NNMT gene sequence with BMI values in the Mexican population, with carriers of the GG and AG genotypes having an increased susceptibility to obesity." (PMID 38919254, 2024). "Although nicotinamide N-methyltransferase (NNMT) has been associated with obesity, how NNMT is regulated during adipogenesis, and the underlying regulatory mechanisms, remain undefined." (PMID 37217546, 2023). "Aberrantly high expression of NNMT has been linked to the development of obesity, type 2 diabetes, various cancers, neurodegenerative diseases, including Alzheimer’s and Parkinson’s disease, and pulmonary hypertension." (PMID 36984839, 2023). "Interventions to reduce Nnmt expression or NNMT enzymatic activity led to body fat loss and improved glucose handling in mice with diet-induced obesity and insulin resistance." (PMID 36104373, 2022). "As summarized in this review, NNMT plays important roles in obesity and T2D and is an attractive therapeutic target to prevent or treat obesity and associated T2D." (PMID 34368359, 2021). "Recently, nicotinamide N-methyltransferase (NNMT) has been emerging as a new mechanism-of-action target in treating obesity and associated T2D." (PMID 34368359, 2021). "Elevated NNMT expression in murine white adipose tissue (WAT) has been associated with obesity and insulin resistance, whereas WAT NNMT knockout was protective." (PMID 34071182, 2021). "Recently, NNMT has been emerging as a new mechanism-of-action target for treatment of obesity and associated T2D." (PMID 34368359, 2021). "Higher NNMT expression and activity in white adipose tissue of mice and humans has been associated with obesity, insulin resistance and type-2 diabetes (T2D)." (PMID 33668468, 2021). "An increase in NNMT expression has also been linked to the pathogenesis of obesity, with small molecule NNMT inhibitors shown to have efficacy at reversing the disease in animal models of obesity." (PMID 33387303, 2021). "NNMT expression in adipose tissue is associated with obesity and insulin resistance, and in embryonic stem cells, the expression of NNMT is believed to help maintain cells in a naive state." (PMID 32992891, 2020). "We previously reported that serum N1-methylnicotinamide (me-NAM), an indicator of nicotinamide N-methyltransferase (NNMT) activity, was associated with obesity, diabetes, and coronary artery disease in Chinese patients." (PMID 29872082, 2018). "Additionally, significant associations were observed between single nucleotide variants in the NNMT gene and energy metabolism, obesity, T2D, hyperlipidemia, and hypertension." (PMID 38919254, 2024). "Additionally, trials of oligonucleotide therapeutics and experiments with some small-molecule NNMT inhibitors in vitro and in preclinical animal models have validated NNMT as a promising therapeutic target to prevent or treat obesity and associated T2D." (PMID 34368359, 2021). "In addition to 5-amino-1MQ, JBSNF-000088 is another NNMT inhibitor that is promising for treatment of obesity and associated T2D." (PMID 34368359, 2021).
Obesity (continued). "The NNMT-MNA-1 axis plays an important role as a regulator of energy metabolism, and SNPs in the NNMT gene may be associated with obesity and energy expenditure." (PMID 32651404, 2020). "Here we explored the association between NNMT gene polymorphisms and obesity." (PMID 29075643, 2017). "Are there any SNPs in NNMT DNA sequence significantly associated with obesity?" (PMID 29075643, 2017). "The use of NNMT inhibitors as a potential obesity treatment has been investigated preclinically, and observational clinical data suggests that increased NNMT expression and activity correlate with increased incidence of Type 2 diabetes (T2D) and risk of obesity, respectively." (PMID 35013352, 2022). "Since NNMT expression is directly determined by the NNMT gene, in our previous works, nineteen SNPs in the NNMT DNA sequence were selected as tagSNPs using Haploview software (Haploview 4.2) to observe the association between NNMT gene polymorphisms and obesity and hyperlipidemia." (PMID 34368359, 2021). "Here, we identified 19 tagSNPs (including rs694539 and rs1941404) across the whole NNMT gene DNA sequence using Haploview software (Haploview 4.2) in the first place and then performed a case-control (fat versus thin) study to explore the association between these tagSNPs and obesity." (PMID 29075643, 2017). "Another study demonstrated that the fat content and obesity-related gene (FTO) promote M2-TAM polarization by regulating m6A-dependent demethylation of Nicotinamide N-methyltransferase (NNMT) in CAFs, thereby driving gastric cancer progression." (PMID 40977700, 2025). "The epigenetic significance of nicotinamide N-methyltransferase (NNMT) has recently been suggested in obesity and T2DM." (PMID 38397953, 2024). "NNMT also plays a crucial role in lipid metabolism, adipocyte differentiation, and potentially obesity-related regulatory pathways." (PMID 39035994, 2024). "Multiple studies have reported a conspicuous upregulation of NNMT expression in WAT among mice prone to obesity compared to their obesity-resistant counterparts." (PMID 38919254, 2024). "As observed in NNMT knockdown experiments, NNMTis counteract obesity by influencing NAD+ rescue and SAM-related pathways." (PMID 38921477, 2024). "Previous investigations have highlighted elevated NNMT expression in the liver and white adipose tissue (WAT) of diabetic mice and obese, with evidence suggesting that downregulating NNMT expression can mitigate diet-induced IR and obesity." (PMID 38919254, 2024). "Similar to the NNMT knockdown experiments, NNMT inhibitors reversed obesity by modulating NAD+ rescue and the pathways mediated by SAM." (PMID 38919254, 2024). "NNMT’s influence on obesity predominantly stems from its regulatory role in energy metabolism, particularly through NAM methylation, which significantly impacts energy modulation." (PMID 38919254, 2024). "Metabolomic analyses reveal elevated levels of urinary MNAM in db/db male mice and obese Zucker rats, suggesting increased NNMT activity in obesity and type 2 diabetes." (PMID 38029302, 2024). "Nicotinamide N-methyltransferase (NNMT) is a methylase, and its expression is positively correlated with obesity and insulin resistance." (PMID 35603729, 2022). "Small‐molecule inhibitors of NNMT have been developed in recent years and are discussed as therapeutics for metabolic diseases, such as diabetes, obesity and fatty liver disease." (PMID 35678045, 2022). "Another role of NNMT that has been discussed in the setting of diet-induced obesity is lipotoxicity." (PMID 36104373, 2022). "NNMT is touted as an attractive target for developing small molecule inhibitors to treat obesity and type 2 diabetes." (PMID 36104373, 2022). "NNMT is a positive regulator of gluconeogenesis and its knockdown in adipose tissue prevented diet-induced obesity in mice." (PMID 35756670, 2022).
Obesity (continued). "NNMT increases energy expenditure in a cell-autonomous manner by regulating histone methylation, polyamine flux, and SIRT protein, which suggests that NNMT is a potential target of diet-induced obesity and type 2 diabetes." (PMID 35756670, 2022). "According to these findings, it was proposed that NNMT plays important roles in energy metabolism and in the development of a number of disorders, such as obesity, diabetes, aging, Parkinson's disease, and cancer." (PMID 34368359, 2021). "The majority of the first small-molecule inhibitors developed were focussed upon targeting NNMT in obesity and alcohol-related fatty liver disease." (PMID 34680055, 2021). "Usually, increased energy expenditure is used to explain the protective effects of NNMT inhibition or NNMT knockdown against diet-induced obesity." (PMID 34368359, 2021). "Knockdown of NNMT has been reported to have protective effects against diet-induced obesity, including lowering fat mass, serum triglycerides, free fatty acids, as well as increasing insulin sensitivity in mice with elevated energy consumption." (PMID 32895402, 2020). "An increase of NNMT expression has been observed in obesity and diabetes, probably because NNMT controls lipid, cholesterol, and glucose metabolism by stabilizing SIRTs." (PMID 31510030, 2019). "To explore the pathological role of NNMT expression in the development of obesity and fatty liver, we generated Tg mice that overexpressed NNMT." (PMID 29872122, 2018). "Higher NNMT expression and MNA concentrations have been associated with obesity and type-2 diabetes." (PMID 29483571, 2018). "The production of 1MNA by nicotinamide N-methyltransferase (NNMT) is proposed to contribute to diet induced obesity through regulation of NAD and ultimately Sirt1 signaling." (PMID 29324762, 2018). "NNMT knockout was found to protect against diet induced obesity proposed to be through the regulation of NAD and S-adenosylmethionine (SAM) levels." (PMID 29324762, 2018). "Additional factors contributing to the energy expenditure and obesity resistance of the mice include the reduced expression of NNMT in the liver, muscle, and potentially other tissues and downstream effects on NAD+ metabolism and/or the polyamine pathway." (PMID 25934505, 2015). "Perturbations of polyamine synthesis have been linked to changes in adiposity, and mice expressing reduced levels of nicotinamide N-methyltransferase (NNMT), which influences polyamine synthesis, are obesity-resistant." (PMID 25934505, 2015). "Recent reports of small molecule NNMT inhibitors, which increase cellular NAD+ levels leading to metabolic benefits such as the reversal of diet-induced obesity and prevention of muscle senescence supports the viability of modulating NNMT activity to achieve these goals." (PMID 38212381, 2024). "The demonstration that the administration of antisense oligonucleotides targeting NNMT to animals led to reduced weight gain and enhanced insulin sensitivity has prompted the development of NNMT inhibitors (NNMTis) for the treatment of obesity and type 2 diabetes." (PMID 38921477, 2024). "Interestingly, a genetic knock-down of NNMT expression in white adipose tissue and the liver protected the mice from high-fat-diet-induced obesity by augmenting cellular energy expenditure, further making NNMT an interesting drug target." (PMID 36766842, 2023). "Moreover, NNMT knockdown in mice fed HFD protects against diet-induced obesity, with a concomitant increase of WAT NAD+ and modulated expression of several upstream and downstream genes, including SIRT1 targets." (PMID 37761000, 2023). "Nicotinamide N-methyltransferase, which catalyzes methylation of niacinamide to generate 1-methylnicotinamide, has been proposed as a promising therapeutic target to prevent or treat obesity and diabetes." (PMID 37110210, 2023).
Obesity (continued). "For example, the NNMT gene may play a role in energy metabolism, fatty acid oxidation, liver fat accumulation, diabetes, obesity, and cardiovascular diseases." (PMID 38042786, 2023). "Furthermore, NNMT knockdown increases energy expenditure and protects cells from diet-induced obesity." (PMID 37371959, 2023). "Selective NNMT inhibitors have been developed that could be used for treatment of several pathological conditions including cancer, obesity, metabolic disorders, and alcohol-related fatty liver disease." (PMID 36766842, 2023). "Surprisingly, the pronounced improvement in glucose tolerance upon treatment with JBSNF-00028 was observed in both wild-type and NNMT k.o mice with diet-induced obesity, pointing towards an additional glucose-normalizing effect of the compound beyond NNMT inhibition." (PMID 36104373, 2022). "Therefore, while protection from diet-induced obesity and impaired glucose metabolism has been consistently observed upon NNMT deletion, knockdown or inhibition, the molecular details and pathways mediating these effects remain to be further elucidated." (PMID 36104373, 2022). "Nonetheless, NNMT has different roles in obesity, type 2 diabetes, and hepatic disease." (PMID 35756670, 2022). "Evidence has shown that NNMT plays important roles in obesity and T2D and that NNMT inhibition significantly increases energy expenditure, reduces body weight and white adipose mass, improves insulin sensitivity, and normalizes glucose tolerance and fasting blood glucose levels." (PMID 34368359, 2021). "Therefore, more researches are still necessary to reveal the roles and action mechanisms of NNMT in obesity and T2D and to develop therapeutics targeting NNMT." (PMID 34368359, 2021). "Therefore, more researches are necessary to reveal the acting mechanism of NNMT in obesity and T2D and to develop therapeutics targeting NNMT." (PMID 34368359, 2021). "An increase of NNMT expression has been observed in obesity and diabetes." (PMID 31510030, 2019). "Then, why no SNP in NNMT gene has been identified to be significantly associated with obesity in GWASs?" (PMID 29075643, 2017). "Nicotinamide N-methyltransferase (NNMT)-ASO prevents diet-induced obesity in mice." (PMID 28839185, 2017). "The results show that no CGAS concerning NNMT gene and obesity has been carried out to date and that no SNP in NNMT DNA sequence has been identified to be significantly associated with obesity in existing GWASs." (PMID 29075643, 2017). "By increasing energy expenditure NNMT knockdown protected against diet-induced obesity." (PMID 26816084, 2016). "We cannot exclude the possibility that increased NNMT activity in the liver of patients with type 2 diabetes and obesity may, in addition to increased expression in WAT, also contribute to the observed associations in these patients." (PMID 25596852, 2015). "Interestingly, the improvement in glucose tolerance upon treatment with JBSNF-000028 was also observed in NNMT knockout mice with diet-induced obesity, pointing towards the glucose-normalizing effect that may go beyond NNMT inhibition." (PMID 36104373, 2022). "This review will focus on the roles of NNMT in obesity and T2D, as it has been found that the expression of this methyltransferase is elevated in the white adipose tissue and liver of obese people and diabetic mice and that NNMT knockdown protects against diet-induced obesity and insulin resistance." (PMID 34368359, 2021). "In addition to oligonucleotide therapeutics, some small-molecule NNMT inhibitors have been reported recently and several have shown effectiveness in the prevention or treatment of obesity and T2D in vitro or in preclinical animal models, validating NNMT as a pharmacological drug target." (PMID 34368359, 2021).